KATNBL1 (katanin regulatory subunit B1 like 1)
Description:
Regulates microtubule-severing activity of KATNAL1 in a concentration-dependent manner in vitro.
Synonyms: C15orf29; FLJ22557
Tractability: No criterion of Open Targets' tractability assessment is met for any kind of drug.
Gene: Protein-coding gene on chromosome 15 (34,140,365 to 34,210,119, reverse strand). Ensembl gene ENSG00000134152.
Subcellular location: Nucleus; Cytoplasm, cytoskeleton, spindle pole
Subcellular location (Human Protein Atlas): Midbody; Mitotic spindle; Cleavage furrow; Nucleoplasm
Gene Ontology:
Molecular function: protein binding; microtubule binding
Biological process: cytoplasmic microtubule organization; positive regulation of cytoskeleton organization
Cellular component: katanin complex; mitotic spindle; mitotic spindle pole; nucleolus; nucleoplasm; nucleus; microtubule cytoskeleton; spindle pole
Genetic constraint (gnomAD): Loss-of-function variants: 8 observed, 18.6 expected, observed/expected ratio (o/e) 0.43, 90% interval 0.25 to 0.78. The upper end of that interval is the gene's LOEUF score, 0.78, which puts it in group 3 of 6, group 1 being the genes least tolerant of losing a copy. Missense variants: 185 observed, 211.24 expected, observed/expected ratio (o/e) 0.88, 90% interval 0.78 to 0.99. Synonymous variants: 54 observed, 72.36 expected, observed/expected ratio (o/e) 0.75, 90% interval 0.6 to 0.94.
Homologues: Orthologues: chimpanzee KATNBL1 (100% identical), macaque KATNBL1 (99% identical), dog KATNBL1 (94% identical), guinea pig KATNBL1 (93% identical), rabbit KATNBL1 (93% identical), pig KATNBL1 (92% identical), mouse Katnbl1 (86% identical), rat Katnbl1 (84% identical), tropical clawed frog katnbl1 (64% identical), zebrafish katnbl1 (42% identical).